ENSG00000255663 (novel transcript, RBM7-REXO2 readthrough)
Gene: Protein-coding gene on chromosome 11 (114,400,682 to 114,443,932, forward strand). Ensembl gene ENSG00000255663.
Genetic constraint (gnomAD): Missense variants: 105 observed, 134.42 expected, observed/expected ratio (o/e) 0.78, 90% interval 0.67 to 0.92. Synonymous variants: 51 observed, 48.59 expected, observed/expected ratio (o/e) 1.05, 90% interval 0.84 to 1.33.